CXCL10 (C-X-C motif chemokine ligand 10)
Diseases named in the same sentence as CXCL10 in open-access papers (continued):
Sharing a sentence is not in itself a finding about the gene and the disease.
infection (continued). "Another study has demonstrated a TLR3-depdendent IP10/CXCL10 response to infection with Xenotropic murine leukemia virus-related virus (XMRV) in two cell lines." (PMID 33202596, 2020). "CXCL10 is a pro-inflammatory chemokine involved primarily in the recruitment of T cells to the site of infection, allowing for amplification of an inflammatory, antimicrobial immune response." (PMID 33106516, 2020). "The levels of mRNAs for chemokines Ccl2, Ccl5, and Cxcl10 remained higher at 6 days after infection in spinal cords of Y114A-infected than WT-infected mice (P < 0.0001)." (PMID 32047134, 2020). "We found that both MLE-12 cells and polarized mouse tracheal epithelial cells (mTECs) were susceptible to infection with Influenza A and released proinflammatory cytokines, including CCL2, CCL5, CXCL1, and CXCL10, in response to replicating virus." (PMID 33374950, 2020). "We also observed a higher expression of CXCL10 in the heart of infected mice on day 15 after infection." (PMID 32574175, 2020). "A significantly decreased induction of some type I IFN and CXCL10, hence IFN-gamma genes in KO mouse lungs in response to PR8 infection explains the increased susceptibility of these mice to infection." (PMID 32640546, 2020). "(E) Fold induction of CXCL10 after infection of THP-1 cells with HIV-GFP -Vpr, HIV-GFP +Vpr, or HIV-1 particles lacking Vpr and genome, at indicated doses measured by reverse transcriptase SG-PERT assay." (PMID 33300875, 2020). "This newly described TNFR2-mediated induction of CXCL10 is thought to be relevant for virus elimination in the early stage of infection downstream of the TLR3-dependent signaling cascade." (PMID 32089645, 2020). "In the current study, GD-SH-01 induced a high level of chemokines in late stage of infection due to its strong replication in vivo, which facilitated CXCL10 to recruit T cells into CNS and initiate the breakdown of BBB permeability." (PMID 32153520, 2020). "In hamsters, which are a model for human NiV disease, upregulation of CXCL10 closely correlates with viral antigen expression, initially increasing followed by a decrease in expression the day preceding lethal outcome of the infection." (PMID 32226041, 2020). "Unexpectedly, most SARS patients experience a robust upregulation of type-I interferon during the early phase of infection that occurs concurrently with an upregulation in the expression of IFN-stimulated chemokines (CXCL-10 and CCL-2)." (PMID 32922406, 2020). "Screening of a panel of 49 cytokines for basolateral secretion from infected NECs identified CXCL10 as the only cytokine significantly induced upon infection, at comparable levels in both wild-type and Δ382 infected cells." (PMID 33284849, 2020). "There was a clear dose effect of HIV infection with increasing CXCL10 production with an increasing multiplicity of infection (MOI) in both cell lines." (PMID 32898182, 2020). "A single unilateral injection of EcoHIV (1 × 106 pg) directly into the caudate putamen resulted in a significant increase in inflammatory markers (TNFα, IL-1β, IFNγ, CCL2, CCL3, CXCL10) 5 days after infection." (PMID 31263138, 2019). "L. major WT promastigotes had no induction of CXCL10 protein relative to uninfected cells, while L. major Δgp63 infection resulted in a significant induction of CXCL10 protein." (PMID 31440475, 2019). "Because CXCL10 coordinates the recruitment of CXCR3+ T cells during infection, we next tested if GP63 cleavage of CXCL10 impacts T cell recruitment." (PMID 31440475, 2019). "With the early upregulation of CXCL10 transcript, NK cells recruited during infection produce IFNγ that contributes to Th1 differentiation." (PMID 31440475, 2019). "Specifically, transcription of Cxcl10 is upregulated in T resident-memory (Trm) cells after secondary infection, and antibody blockade of CXCR3 prevents recruitment of circulating CD4+ T cells to the site of infection." (PMID 31440475, 2019).
infection (continued). "The increased transcriptional expression of interferon gamma-induced protein 10 (CXCL10/IP-10) and interferon beta (IFNβ) was detected in podocytes and mesangial cells at 96 h post-infection." (PMID 31252545, 2019). "THP-1 monocytes stimulated with LPS upregulate significant production of CXCL10 protein, but infection with live S. Typhimurium dramatically impaired this CXCL10 induction." (PMID 31440475, 2019). "The protein levels of interleukin (IL)-1α, TNFα, MIG (CXCL9), and IP-10 (CXCL10) were significantly higher in ZBP1−/− mice compared to the WT mice at day 2 after infection." (PMID 31572318, 2019). "First, the host upregulates CXCL10 transcription throughout infection and cells expressing CXCR3 are expanded after infection." (PMID 31440475, 2019). "GP63 cleavage of CXCL10 occurs throughout in vitro infection and abrogates CXCR3-dependent T cell migration." (PMID 31440475, 2019). "While CXCL8/IL8 attracts neutrophils, basophils and T-cells to the site of the infection, CXCL10 is chemotactic for monocytes and T-lymphocytes by binding to CXCR3." (PMID 31619718, 2019). "Further investigation beyond the scope of this manuscript will be required to elucidate the implications of CXCL10 cleavage in other infection contexts and animal models." (PMID 31440475, 2019). "Many ISGs are potent inflammatory chemokines, such as CXCL10, a chemotactic factor for monocytes vital for attracting these phagocytes to areas of infection or damage." (PMID 31385572, 2019). "CXCL10 is an important chemoattractant induced by many other viruses upon infection, resulting in recruitment of immune cells." (PMID 31289185, 2019). "Herein, a single unilateral injection of EcoHIV (1 × 106 pg) directly into the caudate putamen resulted in a significant increase in inflammatory markers TNFα, IL-1β, IFNγ, CCL2, CCL3 and CXCL10 5 days after infection." (PMID 31263138, 2019). "The RSV NS1 and NS2 proteins inhibit IFN-α and IFN-β to establish infection, however, in our study we observed an increase in CXCL10, an interferon induced protein, after minocycline treatment." (PMID 31405261, 2019). "To test the capacity of L. major to suppress CXCL10 in both the promastigote and amastigote stage of infection, we utilized PMA differentiated THP-1 monocytes as an intracellular macrophage model of infection." (PMID 31440475, 2019). "Consistent with CXCL10 playing a protective role during infection, multiple studies show that recruitment of CXCR3-expressing cells actively shapes the immune response." (PMID 31440475, 2019). "We observed significantly increased transcript levels of NOS2, CXCL9, and CXCL10 beginning at day 5 post-infection in DCs isolated from H99γ infected mice compared to DCs from H99 infected mice." (PMID 31273203, 2019). "High levels of TNF-α, IL-1β, and CXCL10 are present in amniotic fluid from pregnancies complicated by infection compared to uninfected controls." (PMID 31133875, 2019). "CXCL10 expression was significantly increased upon infection of VA1 in primary astrocytes and SK-N-SH cells." (PMID 31289185, 2019). "Our data demonstrate that CXCL11 is significantly up-regulated during PHI, positively correlating with CXCL9 and CXCL10, and negatively associated with CD4+ T-cell count at 1-year-infection point." (PMID 31836011, 2019). "In contrast, a significant upregulation of IL-8/CXCL8 and IP-10/CXCL10 was detected upon infection with JEV and ZIKV." (PMID 31057517, 2019). "pDCs are capable of producing various chemokines such as CCL4, CCL5, and CXCL10, which attract T cells to sites of infection and inflammation." (PMID 30984181, 2019). "The proinflammatory cytokine CXCL10/IP-10 is known to stimulate the migration and activation of immune effector cells to sites of infection." (PMID 31252545, 2019). "Among its target genes, we observed increased expression of IL6, IL8, CCL5 and CXCL10 at different time points post infection." (PMID 31575039, 2019).
infection (continued). "In fact, several of the cytokines seen here are the same neutrophil chemokines (Cxcl5, Ccl4, Cxcl1) and T-cell chemokines (Cccl5, Cxcl10, Ccl17) that were highlighted in the infection effect analysis." (PMID 30134832, 2018). "In responses to VACV-70, HSV-60, dsDNA, and cGAMP, Trim29-/- macrophages also produced significantly elevated CCL5 and CXCL10, the chemokines that are important to recruit immune cells to the site of infection and eliminate viral infection." (PMID 29581886, 2018). "Our results suggest that the MERS-N protein is one of the contributing factors for CXCL10 up-regulation during infection." (PMID 30242057, 2018). "We identified a source of CXCL10 production at the site of infection in the lung, where M. tuberculosis-infected alveolar macrophages secrete high levels of CXCL10." (PMID 30026741, 2018). "The serum cytokines such as IFN-β, CXCL10, and IL-6 induced by infection of HSV-1, VACV, and MCMV were impaired in Zcchc3−/− in comparison to Zcchc3+/+ mice, and ZCCHC3-deficiency renders the mice more susceptible to HSV-1- or VACV-induced death." (PMID 30135424, 2018). "The expression of CCL5 and CXCL10 initiates peripheral leukocytes recruitment at the site of infection leading to aggravated inflammatory response, which has the deleterious effect on neurons." (PMID 30001342, 2018). "qPCR analysis indicated that transcription of downstream genes including Ifnb1, Cxcl10, and Il6 following infection with HSV-1 and VACV was markedly inhibited in Zcchc3−/− mouse bone marrow-derived macrophages (BMDMs) and dendrite cells (BMDCs)." (PMID 30135424, 2018). "We observed a striking lower plasma activity of soluble DPP4 in TB patients compared to healthy individuals further supporting the concept that CXCL10 truncation is an early event occurring at the site of infection." (PMID 30026741, 2018). "Th1 cells that are essential for infection control are recruited to the site of infection directed by chemokines, predominantly CXCL10." (PMID 30026741, 2018). "We then repeated the infection and measured CXCL10 and IFN-β mRNA expression 6 h after HT-DNA transfection." (PMID 29491158, 2018). "The LJM17-immunized dogs presented a prolonged pattern of pro-inflammatory response that persisted until 4 months after infection, with the exception of IL-2, CXCL10, IL-8, and CCL2." (PMID 30519235, 2018). "For example, CXCL10 released from DCs infected with Mycobacterium tuberculosis enhanced NK cell migration to sites of infection where they destroyed Mycobacterium infected cells." (PMID 30177958, 2018). "We found that induction of serum cytokines including IFN-β, CXCL10, and IL-6 following infection of the DNA viruses HSV-1, VACV, and MCMV was severely impaired in Zcchc3−/− in comparison to Zcchc3+/+ mice." (PMID 30135424, 2018). "Considering that S. pneumoniae-infected mice exhibited significantly greater serum levels of IFN-β, IFN-γ, CXCL9, and CXCL10 than S. aureus-infected mice, we explored the power of these four biomarkers to discriminate between the two infection groups." (PMID 29988532, 2018). "Gene expression analyses have also shown that CXCL10 and CXCL11 are highly upregulated early during infection with highly pathogenic H1N1 and H5N1 and associated with elevated tissue damage." (PMID 30568659, 2018). "CXCL10 binds CXCR3, a receptor expressed on lymphocytes, and in Dengue infections, CXCL10 recruits activated T and NK cells to the site of infection." (PMID 30112159, 2018). "Compared to the control, the rate of proliferation of sensory Fbs (10K) was significantly suppressed by CXCL10-siRNA infection, while the proliferation rate of motor Fbs (10K) was significantly enhanced by CXCL10-siRNA infection." (PMID 30686982, 2018). "Next, we confirmed that the reduction of CXCL9 and CXCL10 reduced the entry of effector T cells into the infection site." (PMID 28751894, 2017).
infection (continued). "The chemokines CXCL9 and CXCL10 have been shown to facilitate entry of T cells into epithelium during infection of mucosal surfaces with HSV-2." (PMID 28407741, 2017). "We have shown that CXCL10 expression was strongly increased during infection, even if the level of viral replication appears very limited in MDMs." (PMID 29215596, 2017). "The upregulation of CXCL10 secretion after Ad infection of mMSCs was confirmed using an ELISA assay, which revealed levels of 800 pg of CXCL10 per mL of supernatant, 24 h after infection." (PMID 28525366, 2017). "In contrast, only a few immunity-related mRNAs encoding chemokines (Cxcl10, Cxcl1, Ccl2) and the invariant chain (CD74) were up-regulated in multiple host cell types after infection." (PMID 28775382, 2017). "Overall, a trend of downregulation dominated the transcriptomic profile under infection, however, the genes C-X-C motif chemokine ligand 10 (CXCL10), IRG6 and CAV1 were upregulated for the majority of the comparisons." (PMID 28727780, 2017). "During the progression of the infection, a significant increase of CXCL10 level in the serum (43.61+5.98 pg/mol) versus controls (p<0.0001) and versus 6 dpi (p = 0.0031) was recorded at 14 dpi." (PMID 28821016, 2017). "In VL, studies in BALB/c mice have shown that CXCL10 is involved in the protective response of infection by L. donovani, inducing a Th1 response through the regulation of the pathway of inflammatory mediators, such as NO and inflammatory cytokines." (PMID 28767981, 2017). "In conclusion, BTV-8 infection induces an inflammatory response in the host characterized by increased IL-6, IL-12 and CXCL10 levels, but IL-1β levels only increased after the third infection." (PMID 28662714, 2017). "In this study, the associated genes (IFIH1, IFNB1, DDX58, CXCL10 and IL12A) in the RIG-I-like receptor signaling pathway were increased obviously at 8 h post-infection(p<0.05), compared to 3 h post-infection." (PMID 28938587, 2017). "Infection of H3N2 and H1N1 viruses causes the upregulation of IL-6, CXCL9, and CXCL10 in cultured human umbilical vein endothelial cells." (PMID 28399143, 2017). "Transcriptional regulation of CXCL10 following infection with Ad vectors, differs significantly from the transcriptional mechanisms activated in response to TNF-α and IFNγ." (PMID 28525366, 2017). "The chemokines CXCL9 and CXCL10 have been shown to facilitate entry into the epithelium during infection of mucosal surfaces with HSV-2." (PMID 28407741, 2017). "Other DEGs of note that were upregulated throughout infection include the monocyte chemoattractant CXCL10 (C-X-C Motif Chemokine Ligand 10) and the C1 inhibitor SERPING1 (Serpin Family G Member 1)." (PMID 29123522, 2017). "Cytokine production in vitro - Treatment with CXCL10 (100 ng/mL) in macrophages infected by L. infantum inhibited IL-4 production (significant at 24 h post-infection; p < 0.01) and IL-10 (p < 0.001) in two time periods." (PMID 28767981, 2017). "It should be mentioned however that for a minor number of individual genes in distinct cell types, RNAseq and RT-qPCR data indicated different levels of regulation after infection (e.g., Cxcl10 and Ttpal in fibroblasts)." (PMID 28775382, 2017). "There was a significant reduction in TNF-α, IL-6, and CXCL10 transcripts during Opal524R infection at this time point." (PMID 29138302, 2017). "The levels of MIP1α/Ccl3, IL-1, and IFNγ-inducible factors, such as ICAM-1, IP10/Cxcl10 and Cxcl9 were all increased in the chronic phase of the infection." (PMID 28787450, 2017). "This was complemented by upregulation of all chemokine genes involved in monocyte recruitment on day 3 in H5N1 infection, whereas only two genes (CCL8 and CXCL10) were upregulated in X-179A infection at this time point." (PMID 28405622, 2017).
infection (continued). "Further, although we did not observe significant differences in monocyte recruitment to the footpad, CCL3, CCL4, CCL7, and CXCL10 are all known monocyte chemoattractants that were also significantly reduced during Opal524R infection." (PMID 29138302, 2017). "Strikingly, CXCL10 mRNA levels were significantly higher during infection with both H5N1 and H1N1 in guinea pigs depleted of complement via CVF treatment when compared to controls." (PMID 28418930, 2017). "It has been demonstrated that during MVA infection bystander DCs undergo maturation and are able to produce large amounts of a T cell-activating cytokine–IP-10/CXCL10." (PMID 28604814, 2017). "In contrast, the abundance of Ifnb, Ifna4 or Cxcl10 mRNAs induced by RNA mimic poly(I:C) transfection or RNA virus Sendai virus (SeV) infection was comparable between Rnf185 knockdown and wild-type L929 cells." (PMID 28273161, 2017). "These in vivo data support a direct antimicrobial role for CXCL10 that is unrelated to its interaction with CXCR3 and suggest that CXCL10 is produced locally at a high enough concentration to actively kill the bacteria at sites of infection." (PMID 27165799, 2016). "The concentrations of CCL-5 in the CK/SD/w4 infection were up-regulated to fivefold at 24 hpi (P < 0.01), whereas CXCL-10 was increased up to sevenfold at 18 hpi (P < 0.01)." (PMID 27446066, 2016). "SeV-induced expression of IFN-β, CXCL10, Mx1 and CCL5 in OPN-deficient macrophages was also restored upon infection with lentivirus containing the C-terminal fragment of iOPN." (PMID 27026194, 2016). "Relative expression of CXCL10 correlated with viral load in two of the three experiments at week 24 post infection." (PMID 27902344, 2016). "Pro-inflammatory cytokines (IFN-γ, IL-18, IL-6, TNF-α) and chemokines (CCL2, CCL5, CCL7, CXCL1, CXCL10) were found to be increased in sera of ZIKV-infected mice, indicating that infection causes systemic inflammation." (PMID 27163257, 2016). "In contrast, CK/SD/w3 has more capacity in inducing CCL-5 and CXCL-10 at the later stage of infection." (PMID 27446066, 2016). "CHPV infection of PBMC, Monocytes and B cells strongly stimulated the chemokines (CCL2/MCP-1, CCL5/rantes, CXCL9, CXCL10/IP10) during the course of infection." (PMID 27628855, 2016). "CXCL10 RNA levels before infection correlated with overall plasma viral load only after combining both data sets and with a lower significance level (e.g. AUC wpi 0–8: rs=−0.72, P=0.0017)." (PMID 27902344, 2016). "Overexpressing miR-200a-3p (MIM-200a) in single and mixed IAV/SP-infected cells enhanced the levels of CXCL10 at 24 h post-infection, whereas partial inhibition (INH-200a) downregulated the expression of CXCL10." (PMID 27922126, 2016). "Lentiviral infection of WT iOPN expression plasmid into OPN-deficient macrophages restored SeV-induced expression of IFN-β, CXCL10, Mx1 and CCL5 to the same level as that in WT macrophages." (PMID 27026194, 2016). "The MAVS-independent nature of interferon responses was also observed for IAV, when measuring the ISG CXCL10 in BMDCs infected with high multiplicity of infection (MOI)." (PMID 26893169, 2016). "Elevated levels of Th1 cytokines, such as IP-10/CXCL10 secretion in response to IFN-γ, can be expected in an active infection and are associated with improved survival in C. neoformans meningitis." (PMID 27525140, 2016). "We also observed that up-regulation of hepatic expression of 2OAS-1, RIG-I, TLR3, TLR7, and CXCL10 mRNAs was found as early as 7 days after infection and coincident with serum HCV RNA appearance." (PMID 27788241, 2016). "Higher levels of short CXCL10 were observed in HCV-infected subjects relative to healthy controls, indicating an infection-associated post-translational modification of this chemokine." (PMID 26181438, 2015). "The expression of the CXCL10 gene was particularly greatly increased in response to infection with E. coli." (PMID 26572250, 2015).